TCIM (transcriptional and immune response regulator)
Description:
Seems to be involved in the regulation of cell growth an differentiation, may play different and opposite roles depending on the tissue or cell type. May enhance the WNT-CTNNB1 pathway by relieving antagonistic activity of CBY1. Enhances the proliferation of follicular dendritic cells. Plays a role in the mitogen-activated MAPK2/3 signaling pathway, positively regulates G1-to-S-phase transition of the cell cycle. In endothelial cells, enhances key inflammatory mediators and inflammatory response through the modulation of NF-kappaB transcriptional regulatory activity. Involved in the regulation of heat shock response, seems to play a positive feedback with HSF1 to modulate heat-shock downstream gene expression. Plays a role in the regulation of hematopoiesis even if the mechanisms are unknown (By similarity). In cancers such as thyroid or lung cancer, it has been described as promoter of cell proliferation, G1-to-S-phase transition and inhibitor of apoptosis. However, it negatively regulates self-renewal of liver cancer cells via suppresion of NOTCH2 signaling.
Synonyms: TC-1; C8orf4; TC1; hTC-1
Tractability: Antibody: its Gene Ontology location is reachable by antibodies, with high confidence; the Human Protein Atlas places it where antibodies can reach. PROTAC: ubiquitination databases record sites on it.
Gene: Protein-coding gene on chromosome 8 (40,153,482 to 40,155,310, forward strand). Ensembl gene ENSG00000176907.
Subcellular location: Cytoplasm; Nucleus, nucleolus; Nucleus speckle; Nucleus
Subcellular location (Human Protein Atlas): Nucleoplasm; Cytosol; Plasma membrane
Gene Ontology:
Molecular function: Notch binding; protein binding
Biological process: cellular response to heat; endothelial cell activation involved in immune response; negative regulation of Notch signaling pathway; positive regulation of non-canonical NF-kappaB signal transduction; regulation of cell cycle G1/S phase transition; regulation of DNA-templated transcription
Cellular component: cytoplasm; nuclear speck; nucleolus; nucleus
Genetic constraint (gnomAD): Loss-of-function variants: 3 observed, 5.72 expected, observed/expected ratio (o/e) 0.52, 90% interval 0.24 to 1.34. That is too few expected variants to judge how well the gene tolerates losing a copy. Missense variants: 126 observed, 126.45 expected, observed/expected ratio (o/e) 1, 90% interval 0.86 to 1.15. Synonymous variants: 62 observed, 49.22 expected, observed/expected ratio (o/e) 1.26, 90% interval 1.03 to 1.56.
Homologues: Orthologues: chimpanzee TCIM (98% identical), macaque TCIM (96% identical), rabbit TCIM (93% identical), mouse Tcim (92% identical), rat Tcim (92% identical), dog TCIM (91% identical), pig TCIM (91% identical), guinea pig TCIM (90% identical), tropical clawed frog tcim (65% identical), zebrafish tcima (48% identical), zebrafish tcimb (44% identical).
Diseases named in the same sentence as TCIM in open-access papers:
TCIM is named in the same sentence as 17 diseases in open-access papers, as found by Europe PMC text mining. Sharing a sentence is not in itself a finding about the gene and the disease. The quoted sentences say what the papers report.
liver cancer (5 papers, 2015 to 2023). An epithelial or non-epithelial malignant neoplasm that arises from the liver. "The transcriptional and immune response regulator (TCIM/C8orf4) inhibits the self-renewal of liver cancer stem cells by suppressing NOTCH2 signaling." (PMID 35614477, 2022).
lung carcinoma (2 papers, 2017 to 2023). "TCIM encodes a protein that functions as a positive regulator of the Wnt/beta-catenin signaling pathway and Notch pathway, and found to promote the development of lung cancer." (PMID 36968579, 2023).
medulloblastoma (1 paper, 2025). A malignant, invasive embryonal neoplasm arising from the cerebellum. "This suggests that TCIM may have a specific, though limited, role in medulloblastoma, potentially linked to its low-level expression within the tumor microenvironment." (PMID 40104502, 2025).
cancer (11 papers, 2014 to 2024). A tumor composed of atypical neoplastic, often pleomorphic cells that invade other tissues. "Another gene upregulated after infection of HIBCPP cells is TCIM which is often associated with a lethal course of cancer." (PMID 34863201, 2021). "While, e.g., DCAF7 and CDH2 displayed continuous changes across lineage types occurring during cancer progression, others such as TCIM or BRIP1 were expressed transiently at higher levels in asymmetric or only in symmetric (i.e., only invasive tumor cell) lineages, respectively." (PMID 38553478, 2024).
tumor (3 papers, 2015 to 2025). "For instance, GZMA, TCIM, and OLFML2B were significantly clustered in central (C3) and peripheral (C8) regions of the tumor." (PMID 40104502, 2025).
TCIM also shares sentences with these, for which no sentence is quoted: thyroid cancer (4 papers); papillary thyroid carcinoma (3); acute myeloid leukaemia (1); bladder cancer (1); colon (1); colon cancer (1); cystitis (1); gastric cancer (1); hepatocellular carcinoma (1); lentivirus infection (1); ovarian carcinoma (1); pulmonary fibrosis (1).